HMGCS2 (3-hydroxy-3-methylglutaryl-CoA synthase 2)
Diseases named in the same sentence as HMGCS2 in open-access papers (continued):
Sharing a sentence is not in itself a finding about the gene and the disease.
apocrine breast carcinoma (1 paper, 2014). "Here we have shown for the first time that HMGCS2 was up-regulated in ADCIS and IAC and only rarely found in non-apocrine breast carcinoma." (PMID 25389781, 2014). "Given that AR and HMGCS2 are both overexpressed in IAC, the use of the dual therapy targeting two parallel AR and HMGCS2 pathways may provide an additional benefit for therapeutic attack of breast apocrine carcinoma." (PMID 25389781, 2014).
apocrine carcinomas (1 paper, 2014). "Expression of FABP7 and HMGCS2 by invasive apocrine cancer was further demonstrated by IHC using a well characterized set of apocrine carcinomas in which more than 90% of the tumor cells exhibited cytological features typical of apocrine cells." (PMID 25389781, 2014). "Here we report an analysis of the expression of two novel putative protein biomarkers, FABP7 and HMGCS2, in breast lesions undergoing apocrine differentiation: from benign apocrine metaplasia to invasive apocrine carcinoma." (PMID 25389781, 2014). "Our finding that IACs are characterized by an overexpression of HMGCS2, suggests that the patients diagnosed with apocrine carcinoma might benefit from therapy with HMGCS2 inhibitors." (PMID 25389781, 2014). "It is noteworthy, that in both apocrine carcinoma types, ADCIS and IAC, HMGCS2 displayed only cytoplasmic staining pattern." (PMID 25389781, 2014). "Expression of HMGCS2 and FABP7 is strongly associated with apocrine differentiation; their expression is retained by most invasive apocrine carcinomas (IAC) showing positive immunoreactivity in 100% and 78% of apocrine carcinomas, respectively, as compared to non-apocrine tumors (16.7% and 6.8%)." (PMID 25389781, 2014).
apocrine tumors (1 paper, 2014). "Combination of HMGCS2 with steroidal profile (AR+/ER-/PR-) offers greater sensitivity to detect breast apocrine tumors compared to steroidal profile alone." (PMID 25389781, 2014). "Thus, HMGCS2+/AR+/ER-/PR- profile exhibited a significantly higher sensitivity as compared with the AR+/ER-/PR- phenotype, which only provides a sensitivity of 54,17% for apocrine tumors." (PMID 25389781, 2014).
bladder urothelial carcinoma (1 paper, 2022). "The results show that HMGCS2 has the similar pattern in a variety of tumors, including liver hepatocellular carcinoma (LIHC), bladder urothelial carcinoma (BLCA), brain lower-grade glioma (LGG), and KIRC." (PMID 35479398, 2022).
breast tumors (1 paper, 2014). "In conclusion, HMGCS2 and FABP7 are novel protein markers for apocrine differentiation that are highly conserved among apocrine breast tumors retaining their expression during tumor progression." (PMID 25389781, 2014).
Cachexia (1 paper, 2022). Severe weight loss, wasting of muscle, loss of appetite, and general debility related to a chronic disease. "Bdh1 and HMGCS2 mRNA and protein expression levels were significantly higher in the 2-DG-treated cachexia group than in the untreated cachexia model group, indicating that ketogenesis was activated in response to the 2-DG treatment." (PMID 36230949, 2022).
clear cell renal cell carcinoma (1 paper, 2023). "Overall, HMGCS2 represents a promising therapeutic target for cancer and serves as a prognostic marker associated with mitochondrial-related outcomes in renal clear cell carcinoma." (PMID 37670031, 2023). "Aberrant expression of HMGCS2 in pan-cancer is closely associated with clinical pathology and tumor tissue, suggesting its potential as a therapeutic target for cancer suppression, particularly in clear cell renal cell carcinoma." (PMID 37670031, 2023). "Given that HMGCS2 shows a downregulation trend in many cancer types, it is important to further investigate the consequences of HMGCS2 downregulation in renal clear cell carcinoma and normal human kidney cells." (PMID 37670031, 2023). "We performed ectopic expression of GFP-HMGCS2 in the human renal clear cell carcinoma cell line OSRC2 to investigate the biological functions of HMGCS2 in renal clear cell carcinoma." (PMID 37670031, 2023). "Correlation analysis of clinical case characteristics, genomic heterogeneity, tumor stemness, and overall survival revealed that HMGCS2 is closely related to clear cell renal cell carcinoma (KIRC)." (PMID 37670031, 2023). "Furthermore, we validated HMGCS2 as a tumor suppressor in renal clear cell carcinoma (ccRCC) through in vitro experiments, demonstrating that the loss of HMGCS2 leads to malignant cellular behavior in ccRCC." (PMID 37670031, 2023). "In conclusion, HMGCS2 is abnormally expressed in pan-cancer, may play an important role in anti-tumor immunity, and is expected to be a potential tumor prognostic marker, especially in clear cell renal cell carcinoma." (PMID 37670031, 2023).
Cognitive impairment (1 paper, 2026). Abnormal cognition is characterized by deficits in thinking, reasoning, or remembering. "Thus, HMGCS2 is a key molecular switch of cognitive impairment, and targeting HMGCS2 or β-OHB replenishment appropriately may serve as a novel therapeutic strategy for AD treatment." (PMID 41792234, 2026).
Crohn's colitis (1 paper, 2023). Crohn's disease affecting the colon. "To investigate whether the downregulation of HMGCS2 is specific to UC or concerns IBD globally, we analyzed the expression of this enzyme in colonic tissue samples of active Crohn’s colitis patients and healthy controls." (PMID 37457727, 2023).
cyst (1 paper, 2014). A sac-like closed membranous structure that may be empty or contain fluid or amorphous material. "Accordingly 10 out of the 13 apocrine cyst samples (76,9%) and 26 out of 28 non-apocrine ones (92,8%), were classified for HMGCS2 as positive and negative, respectively (p<0.001)." (PMID 25389781, 2014).
diastolic heart failure (1 paper, 2025). Heart failure caused by abnormal myocardial relaxation during diastole leading to defective cardiac filling. "It is important to note that we did see upregulation of HMGCS2 staining in hypertrophic cardiomyopathy, which presents with diastolic heart failure in the absence of metabolic duress and, perhaps, suggests a more pervasive role of ketone metabolism in hypertrophy/diastolic impairment." (PMID 40211954, 2025).
dyslipidaemia (1 paper, 2020). "HMGCS2 deficiencies due to inborn errors of metabolism were associated with dyslipidaemia, while HMGCS2 activity was considered to potentially be involved in high cardiovascular risk." (PMID 32298312, 2020).
dyslipidemia (1 paper, 2025). "Taken together, knockdown of HMGCS2 attenuated cynaroside’s effects on liver injury and dyslipidemia in C57BL/6J mice with NASH combined with T2DM." (PMID 40867627, 2025).
energy metabolism disorders (1 paper, 2025). "Intervention targeting the phosphorylation of JAK2 and STAT3 may inhibit the JAK2/STAT3/HMGCS2 signaling pathway, thereby alleviating hyperuricemia-induced mitochondrial dysfunction, oxidative stress, and energy metabolism disorders, and potentially improving heart dysfunction." (PMID 40361044, 2025).
esophageal cancer (1 paper, 2023). A primary or metastatic malignant neoplasm involving the esophagus. "In the HPA database, HMGCS2 exhibited significantly lower expression levels in most cell lines, except for RT4 (human bladder transitional cell papilloma cells) and OE19 (human esophageal cancer cells)." (PMID 37670031, 2023).
head and neck squamous cell carcinoma (1 paper, 2022). A squamous cell carcinoma that arises from any of the following anatomic sites: lip and oral cavity, nasal cavity, paranasal sinuses, pharynx, larynx, and salivary glands. "In the normal samples, the expression of HMGCS2 was higher in breast invasive carcinoma (BRCA), head and neck squamous cell carcinoma (HNSCC), kidney chromophobe (KICH), kidney renal clear cell carcinoma (KIRC), kidney renal papillary cell carcinoma (KIRP), SKCM and TGCTs." (PMID 35392063, 2022).
hearing loss (1 paper, 2026). "To elucidate the relationship between LONP1 and lead exposure‐induced hearing loss, we examined the expression levels of LONP1 and its substrate HMGCS2 in the cochlea of lead‐exposed mice." (PMID 41215638, 2026).
Hyperammonemia (1 paper, 2025). An increased concentration of ammonia in the blood. "Only one case of neonatal onset presenting with severe hyperammonemia and coma has recently been described in a Vietnamese cohort of HMGCS2 deficiency." (PMID 40548098, 2025). "Taken together, these factors may have contributed to the development of hyperammonemia in patients with HMGCS2 deficiency." (PMID 40548098, 2025). "The pathophysiology of hyperammonemia in HMGCS2 deficiency remains poorly understood." (PMID 40548098, 2025). "Although hyperammonemia is not a major manifestation of HMGCS2 deficiency, mild elevation of blood ammonia has been noted." (PMID 40548098, 2025). "Additional learning points from the present cases were as follows: First, the delayed definite diagnosis of Patient 1 was due to the HMGCS2 not being included in the Human Phenotype Ontology (HPO) terms for metabolic acidosis and hyperammonemia." (PMID 40548098, 2025).
hypercholesterolaemia (1 paper, 2020). "Interestingly, this pathway is regulated by HMGCS2, the enzyme whose mRNA we found to be overexpressed in the same hypercholesterolaemia blood sera." (PMID 32298312, 2020).
Hyperinsulinemia (1 paper, 2025). An increased concentration of insulin in the blood. "Additionally, insulin is a negative regulator of both the transcription and flux of the rate-limiting ketogenic enzyme, HMGCS2, such that despite similar availability of FFAs, ketogenic potential is likely lower in the setting of (relative) hyperinsulinemia." (PMID 40662191, 2025).
hyperuricemia (1 paper, 2025). An abnormally high level of uric acid. "In conclusion, these findings demonstrate that inhibiting the JAK2/STAT3/HMGCS2 signaling pathway with ruxolitinib and S3I-201 alleviates mitochondrial dysfunction, oxidative stress, and cardiac dysfunction caused by hyperuricemia." (PMID 40361044, 2025). "The role of HMGCS2 in hyperuricemia-induced cardiomyocytes was investigated through HMGCS2 knockout." (PMID 40361044, 2025). "To investigate the pathogenesis of hyperuricemia-related cardiovascular diseases, we performed RNA sequencing on a hyperuricemia mouse model and found that the HMGCS2 expression level was significantly increased." (PMID 40361044, 2025). "Similarly, experimental results further confirmed that knocking out HMGCS2 in AC16 cardiomyocytes significantly reduces hyperuricemia-induced mitochondrial fission, restores mitochondrial membrane potential and ATP production, and decreases oxidative stress levels." (PMID 40361044, 2025). "Model of hyperuricemia-induced mitochondrial dysfunction and oxidative stress in cardiomyocytes involving JAK2/STAT3/HMGCS2 signaling." (PMID 40361044, 2025). "This study aimed primarily to elucidate the role of HMGCS2 and the JAK2/STAT3 signaling pathway in hyperuricemia-induced mitochondrial dysfunction." (PMID 40361044, 2025). "Therefore, future studies using HMGCS2 knockout mice to investigate the mechanisms of hyperuricemia, along with long-term animal studies to evaluate the effects of ruxolitinib and S3I-201 on cardiac function in hyperuricemic mice, may enhance the current findings and yield more insightful results." (PMID 40361044, 2025). "In addition, in vitro, the JAK inhibitor ruxolitinib can alleviate hyperuricemia-induced mitochondrial dysfunction and oxidative stress by affecting the JAK2/STAT3/HMGCS2 signaling pathway." (PMID 40361044, 2025).
intestinal cancer (1 paper, 2019). "In summary, we showed that HMGCS2 expression and βHB concentration are regulated by the Wnt/β-catenin/PPARγ pathway in human intestinal cancer cell lines and mouse intestinal organoid cultures." (PMID 31546785, 2019). "In this study, we showed that Wnt/β-catenin signaling negatively regulates the expression of HMGCS2 and βHB production in two intestinal cancer cell lines." (PMID 31546785, 2019). "In addition, knockdown of HMGCS2 increases glycolysis, which regulates differentiation in intestinal cancer cells." (PMID 31546785, 2019).
leukemia (1 paper, 2018). A malignant (clonal) hematologic disorder, involving hematopoietic stem cells and characterized by the presence of primitive or atypical myeloid or lymphoid cells in the bone marrow and the blood. "Five of the top metabolic genes upregulated in leukemia when compared to CD8+ T cells were Hmgcs2, Chdh, Fbp1, Prodh, and Ldhb." (PMID 30140438, 2018).
liver inflammation (1 paper, 2022). "Patients with T2DM can develop various complications, including fatty liver and liver inflammation, and dysfunction of hepatic lipid metabolism could be improved by activation of Cpt-1, Hmgcs2, and Pparα to enhance hepatic oxidation and the metabolism of adipose tissue." (PMID 35186190, 2022).
lung carcinoma (1 paper, 2023). "Notably, the expression of HMGCS2 was found to be considerably reduced in lung cancer and rectosigmoid junction cancer, and in COAD and LIHC, compared to normal tissues." (PMID 37692839, 2023).
nonalcoholic steatohepatitis (1 paper, 2019). "Mitochondrial 3-hydroxy-3-methylglutaryl-CoA synthase (HMGCS2) delivers lipid-derived energy to liver cells, and suppression of HMGCS2 in the nonalcoholic steatohepatitis livers could indicate impairment of ketogenesis and cholesterol biosynthesis." (PMID 31214284, 2019).
overnutrition (1 paper, 2021). An imbalanced nutritional status resulting from excessive intake of nutrients. "However, the pathogenic process of NAFLD is strongly linked to overnutrition, and lipotoxicity promotes the metabolism of active ketone bodies, accompanied by an increased HMGCS2 activity." (PMID 33647884, 2021).
pregnancy toxemia (1 paper, 2023). "Momelolactone B and silibinin inhibited ketosis in vitro by inhibiting HMGCS2 which suggests that these compounds may be promising therapeutic agents for pregnancy toxemia." (PMID 36837768, 2023). "Pregnancy toxemia in ewes inhibits expression of the ACM-related genes 3-hydroxy-3-methyl-glutaryl-coenzyme A (HMG-CoA), 3-hydroxy-3-methylglutaryl coenzyme A synthase 1 and 2 (HMGCS1 and HMGCS2), and 3-hydroxy-3-methylglutaryl-CoA reductase (HMGCR)." (PMID 36837768, 2023).
rectal tumors (1 paper, 2022). "HMGCS2 is a direct target for c-Myc and c-Myc represses HMGCS2 transcription and its protein expression in c-Myc-dependent colon and rectal tumors." (PMID 36432618, 2022).
sarcopenia (1 paper, 2024). Progressive decline in muscle mass due to aging which results in decreased functional capacity of muscles. "All of this suggest that mammalian HMGCS2 may serve as a potential target for the treatment of sarcopenia." (PMID 39076122, 2024). "Therefore, in addition to developing exogenous β‐HB supplements, the development of inducers or activators of HMGCS2 to augment capacity for endogenous β‐HB production may also be an effective approach to improve sarcopenia." (PMID 39076122, 2024).
Stroke (1 paper, 2024). Sudden impairment of blood flow to a part of the brain due to occlusion or rupture of an artery to the brain. "Accordingly, blockage of FAO‐ketogenesis processes by CPT1α antagonism or HMGCS2 knockdown aggravated the cerebral damage and exacerbated stroke severity." (PMID 38666466, 2024). "Herein, we detected enhanced CPT1α‐mediated FAO and HMGCS2‐induced hepatic ketogenesis processes in experimental stroke using transcriptomic profiling and metabolite assays." (PMID 38666466, 2024). "Meanwhile, blocking FAO‐ketogenesis processes by administration of CPT1α antagonist or shRNA targeting HMGCS2 exacerbated endothelial damage and aggravated stroke severity, whereas BHB supplementation blunted these injuries." (PMID 38666466, 2024). "To further consolidate that adaptive ketogenesis is vital to stroke prognosis, we systematically delivered adeno‐associated virus serotype DJ (AAV‐DJ) carrying short‐hairpin RNA targeting HMGCS2 (sh‐HMGCS2) or scrambled shRNA as a control (sh‐Con) 3 weeks prior to MCAO surgery." (PMID 38666466, 2024). "As expected, knockdown of HMGCS2 resulted in decreased circulating BHB levels after stroke." (PMID 38666466, 2024).
tumor (58 papers, 2014 to 2026). "The aberrant inactivation of HMGCS2 is significantly associated with tumor initiation and progression." (PMID 39857793, 2025). "Overall, our results highlight the strong association between HMGCS2 expression and tumor genomic heterogeneity and stemness, particularly in KIRC." (PMID 37670031, 2023). "HMGCS2 is confirmed as a tumour suppressor, and low expression of HMGCS2 is associated with poor OS and DFS of HCC patients." (PMID 37987033, 2023). "The univariate analysis result show that patients with kidney renal clear cell carcinoma (KIRC) with lower expression of HMGCS2 are associated with worse prognosis and it shows downregulation in tumor samples compared with normal samples." (PMID 35479398, 2022). "Mitochondrial 3-hydroxy-3-methylglutaryl-CoA synthase 2 (HMGCS2) is implicated as having oncogenetic activity in many human neoplasms." (PMID 31493764, 2019). "The demonstration of a direct interaction at the nuclear level between HMGCS2 and PPARα is interesting; besides, other analyses confirmed that the heterodimeric complex binds the Src promoter region and induced genes linked to tumor invasion." (PMID 29966227, 2018). "Tumor grade (G) was associated with HMGCS2 expression in STES, KIPAN, HNSC, KIRC, and LIHC." (PMID 37670031, 2023). "To further investigate whether HMGCS2 is associated with prognosis in different tumor types, we perfomed the pan-cancer analysis for HMGCS2 in ToPP using the pan-cancer analysis module." (PMID 35479398, 2022). "The other is that VHL is suggested as mutated as an early event for tumor, and HMGCS2 may have a negative regulation of tumor angiogenesis." (PMID 35479398, 2022). "Thus, we investigated the association of HMGCS2 with tumor stemness." (PMID 37670031, 2023). "In studies describing a tumor-promoting role, the expression of HMGCS2 is elevated in tumor cells, an upregulation that is mediated by tumor-associated fibroblasts." (PMID 40305364, 2025). "For instance, a downregulation of HMGCS2 mediated by miR-107 was observed in hepatocellular carcinoma, accelerating tumor growth and migration." (PMID 39857793, 2025). "Tumor that became resistant to entrectinib in mouse showed overexpression of HMGCS2 compared to the vehicle control, which was confirmed by immunohistochemistry (IHC) and western blot analysis." (PMID 38923428, 2024). "HMGCS2 is a key enzyme in ketogenesis, and several previous studies have suggested an inhibitory effect on tumor growth, migration, and angiogenesis through ketone synthesis in mitochondria." (PMID 38923428, 2024). "HMGCS2 is a mitochondrial enzyme involved in the ketogenic pathway and can be a tumor suppressor by altering lipid metabolism and adjusting cholesterol synthesis." (PMID 36895470, 2023). "Despite our comprehensive pan-cancer analysis providing insights into the tumor suppressor role of HMGCS2, there are significant limitations." (PMID 37670031, 2023). "HMGCS2 expression was also correlated with primary tumor status (T) in BRCA, ESCA, STES, KIPAN, KIRC, LIHC, and CHOL (P < 0.05)." (PMID 37670031, 2023). "Specifically, we evaluated the differential expression of ENSG00000134240 (HMGCS2) between normal and tumor samples in different tumor types." (PMID 37670031, 2023). "HMGCS2 was significantly downregulated in 15 tumor types within the TCGA database, including LUAD, KIRC, and LIHC (P < 0.05)." (PMID 37670031, 2023). "In HCC and prostate cancer, ketogenesis-related hydroxy-methyl-glutaryl-CoA synthase 2 (HMGCS2) inhibits tumor proliferation and metastasis, whereas exogenous ketone bodies also show the similar effects in pancreatic cancer." (PMID 36508088, 2023). "Further investigations should focus on unraveling the tumor suppressor mechanism of HMGCS2 and validating its correlation with the tumor immune microenvironment." (PMID 37670031, 2023).